Y_RNA (Y RNA )
Gene: Miscellaneous RNA gene on chromosome X (112,661,657 to 112,661,768, forward strand). Ensembl gene ENSG00000200436.
Homologues: Orthologues: chimpanzee Y_RNA (99% identical), macaque Y_RNA (98% identical). Paralogues in human: Y_RNA (87% identical), Y_RNA (86% identical), RNY1P5 (85% identical), Y_RNA (85% identical), Y_RNA (83% identical), RNY1 (82% identical), Y_RNA (82% identical), Y_RNA (81% identical), Y_RNA (80% identical), RNY1P2 (79% identical), RNY1P6 (79% identical), Y_RNA (79% identical), and 95 more.